FMR1NB (FMR1 neighbor)
Synonyms: CT37; FLJ25736; NY-SAR-35; NYSAR35
Tractability: Antibody: UniProt predicts a signal peptide or a membrane-spanning region.
Gene: Protein-coding gene on chromosome X (147,981,337 to 148,026,665, forward strand). Ensembl gene ENSG00000176988.
Subcellular location: Membrane
Subcellular location (Human Protein Atlas): Acrosome
Gene Ontology:
Cellular component: membrane
Homologues: Orthologues: chimpanzee FMR1NB (92% identical), macaque FMR1NB (78% identical), dog FMR1NB (48% identical), mouse Fmr1nb (32% identical), rat Fmr1nb (31% identical).
Diseases named in the same sentence as FMR1NB in open-access papers:
FMR1NB is named in the same sentence as 11 diseases in open-access papers, as found by Europe PMC text mining. Sharing a sentence is not in itself a finding about the gene and the disease. The quoted sentences say what the papers report.
lung carcinoma (4 papers, 2012 to 2024). "Fragile X Mental Retardation 1 Neighbor (FMR1NB) expression has been observed in sarcoma, melanoma, esophageal cancer, lung cancer and breast cancer and correlates with advanced grade and poor prognosis in glioma." (PMID 38596293, 2024).
cancer (3 papers, 2015 to 2024). A tumor composed of atypical neoplastic, often pleomorphic cells that invade other tissues. "Out of these, FMR1NB, CTAG1A and MAGEA9B are cancer/testis antigens." (PMID 25884295, 2015).
FMR1NB also shares sentences with these, for which no sentence is quoted: tumor (2 papers); adenocarcinoma (1); breast carcinoma (1); glioma (1); Infertility (1); multiple myeloma (1); prostate tumor (1); sarcoma (1); squamous cell carcinoma (1).